SOX21-AS1 (SOX21 antisense RNA 1)
Gene: Long non-coding RNA gene on chromosome 13 (94,703,454 to 94,803,430, forward strand). Ensembl gene ENSG00000227640.
Diseases named in the same sentence as SOX21-AS1 in open-access papers:
SOX21-AS1 is named in the same sentence as 3 diseases in open-access papers, as found by Europe PMC text mining. Sharing a sentence is not in itself a finding about the gene and the disease. The quoted sentences say what the papers report.
Alzheimer disease (1 paper, 2023). A progressive, neurodegenerative disease characterized by loss of function and death of nerve cells in several areas of the brain leading to loss of cognitive function such as memory and language. "According to previous studies, the lncRNA SOX21 antisense RNA 1 (SOX21-AS1) can alleviate oxidative stress and inhibit neuronal apoptosis in Alzheimer's disease mice and is associated with disease development." (PMID 37400520, 2023).
cancer (1 paper, 2019). A tumor composed of atypical neoplastic, often pleomorphic cells that invade other tissues. "LncRNA SOX21 antisense RNA 1 (SOX21-AS1) dysregulated in many types of human cancer, and functioned as tumor suppressor or promoter depending on tumor types." (PMID 30992391, 2019).
SOX21-AS1 also shares sentences with these, for which no sentence is quoted: tumor (1 paper).